PDZD11 (PDZ domain containing 11)
Description:
Mediates docking of ADAM10 to zonula adherens by interacting with PLEKHA7 which is required for PLEKHA7 to interact with the ADAM10-binding protein TSPAN33.
Synonyms: AIPP1; PDZK11; PISP
Tractability: Antibody: UniProt places it where antibodies can reach, with high confidence; its Gene Ontology location is reachable by antibodies, with medium confidence. PROTAC: ubiquitination databases record sites on it; its protein half-life has been measured.
Gene: Protein-coding gene on chromosome X (70,281,118 to 70,290,596, reverse strand). Ensembl gene ENSG00000120509.
Subcellular location: Secreted (Isoform 2); Cytoplasm (Isoform 1); Cell junction, adherens junction; Cell membrane
Pathways (Reactome):
Metabolism: Biotin transport and metabolism; Vitamin B5 (pantothenate) metabolism
Transport of small molecules: Ion transport by P-type ATPases; Transport of vitamins, nucleosides, and related molecules
Immune System: Ion influx/efflux at host-pathogen interface
Gene Ontology:
Molecular function: protein binding; protein-macromolecule adaptor activity
Biological process: pore complex assembly; neurotransmitter secretion; regulation of synaptic assembly at neuromuscular junction; synaptic vesicle transport
Cellular component: cytoplasm; plasma membrane; pore complex; basolateral plasma membrane; cell-cell junction; cytosol; adherens junction; extracellular region; presynapse
Homologues: Orthologues: chimpanzee PDZD11 (100% identical), pig PDZD11 (98% identical), guinea pig PDZD11 (97% identical), mouse Pdzd11 (97% identical), macaque PDZD11 (93% identical), zebrafish pdzd11 (89% identical), tropical clawed frog pdzd11 (82% identical), dog PDZD11 (81% identical), rat Pdzd11 (79% identical), Drosophila melanogaster veli (36% identical), Caenorhabditis elegans lin-7 (31% identical). Paralogues in human: LIN7B (39% identical), LIN7C (37% identical), LIN7A (36% identical).
Diseases named in the same sentence as PDZD11 in open-access papers:
PDZD11 is named in the same sentence as 9 diseases in open-access papers, as found by Europe PMC text mining. Sharing a sentence is not in itself a finding about the gene and the disease. The quoted sentences say what the papers report.
liver cancer (1 paper, 2021). An epithelial or non-epithelial malignant neoplasm that arises from the liver. "In particular, we demonstrated that PDZD11 is aberrantly expressed in human liver cancer tissues and cell lines." (PMID 34093661, 2021). "Consistently, protein analysis involving eight patients (including eight tumor tissue and eight matched adjacent normal tissues) diagnosed with liver cancer confirmed that PDZD11 abundance was elevated in LIHC tissues." (PMID 34093661, 2021). "Further, we verified the expression of PDZD11 in LIHC tissues, various human liver cancer cell lines and matched normal hepatocytes." (PMID 34093661, 2021). "However, to the best of our knowledge, no study has investigated the role of PDZD11 in liver cancer." (PMID 34093661, 2021).
lymph node metastasis (1 paper, 2021). "According to subgroup analysis based on race, gender, age, weight, and lymph node metastasis status, the mRNA expression of PDZD11 in LIHC patients was evidently higher than that in healthy individuals." (PMID 34093661, 2021).
uterine corpus endometrial carcinoma (1 paper, 2021). A endometrial carcinoma (disease) that involves the body of uterus. "It was shown that the mRNA level of PDZD11 was significantly upregulated in bladder, breast, gallbladder, esophagus, kidney, liver, lung, gastric, thyroid, and uterine corpus endometrial carcinoma." (PMID 34093661, 2021).
tumor (3 papers, 2021 to 2025). "Chen’s group demonstrated that the expression of PDZD11 increased in tumor tissues and was associated with poor prognosis." (PMID 36834630, 2023). "Taken together, abnormal expression of PDZD11 may modulate tumor cell proliferation, invasion, metastasis, and the development of LIHC by regulating these targets." (PMID 34093661, 2021). "The highest mRNA expression of PDZD11 was found in stage 3 and/or tumor grade 3 cases." (PMID 34093661, 2021). "The reason why mRNA expression of PDZD11 in stage 3 and/or tumor grade 3 seemed to be higher than that in stage 4 and tumor grade 4 may be due to the small number of samples." (PMID 34093661, 2021). "Therefore, overexpression of PDZD11 in LIHC could not be ruled out, which is a self-protective feedback regulation mechanism that inhibits tumor metastasis." (PMID 34093661, 2021).
cancer (2 papers, 2021 to 2022). A tumor composed of atypical neoplastic, often pleomorphic cells that invade other tissues. "To explore whether high expression levels of PDZD11 are associated with cancer-promoting or tumor suppressor genes, we evaluated the prognostic value of PDZD11 mRNA expression in patients with LIHC using the DriverDBV3 database." (PMID 34093661, 2021).
PDZD11 also shares sentences with these, for which no sentence is quoted: hepatocellular carcinoma (2 papers); cyst (1); meningitis (1); Usher syndrome (1).